CCNDBP1 (cyclin D1 binding protein 1)
Description:
May negatively regulate cell cycle progression. May act at least in part via inhibition of the cyclin-D1/CDK4 complex, thereby preventing phosphorylation of RB1 and blocking E2F-dependent transcription.
Synonyms: DIP1; GCIP; HHM
Tractability: PROTAC: ubiquitination databases record sites on it; its protein half-life has been measured.
Gene: Protein-coding gene on chromosome 15 (43,185,118 to 43,197,177, forward strand). Ensembl gene ENSG00000166946.
Subcellular location: Cytoplasm; Nucleus
Subcellular location (Human Protein Atlas): Nucleoplasm; Nuclear bodies
Gene Ontology:
Molecular function: protein binding
Cellular component: nuclear body; nucleoplasm; nucleus; cytoplasm
Genetic constraint (gnomAD): Loss-of-function variants: 30 observed, 32.96 expected, observed/expected ratio (o/e) 0.91, 90% interval 0.68 to 1.24. The upper end of that interval is the gene's LOEUF score, 1.24, which puts it in group 5 of 6, group 1 being the genes least tolerant of losing a copy. Missense variants: 350 observed, 350.19 expected, observed/expected ratio (o/e) 1, 90% interval 0.92 to 1.09. Synonymous variants: 122 observed, 130.15 expected, observed/expected ratio (o/e) 0.94, 90% interval 0.81 to 1.09.
Homologues: Orthologues: chimpanzee CCNDBP1 (99% identical), rabbit CCNDBP1 (86% identical), pig CCNDBP1 (84% identical), dog CCNDBP1 (84% identical), guinea pig CCNDBP1 (80% identical), mouse Ccndbp1 (80% identical), macaque CCNDBP1 (79% identical), rat Ccndbp1 (77% identical), tropical clawed frog ccndbp1 (42% identical), zebrafish ccndbp1 (39% identical).
Diseases named in the same sentence as CCNDBP1 in open-access papers:
CCNDBP1 is named in the same sentence as 28 diseases in open-access papers, as found by Europe PMC text mining. Sharing a sentence is not in itself a finding about the gene and the disease. The quoted sentences say what the papers report.
hepatocellular carcinoma (4 papers, 2014 to 2022). A malignant tumor that arises from hepatocytes. "Hepatocellular carcinoma (HCC) cells and tissues obtained from Ccndbp1 knockout mice were used for the in vitro and in vivo examination of the molecular mechanisms of CCNDBP1 associated with the recovery of cells from DNA damage." (PMID 35160302, 2022). "The mice with livers lacking CCNDBP1 expression had an early development of hepatocellular carcinoma." (PMID 34631521, 2021).
liver cancer (3 papers, 2014 to 2022). An epithelial or non-epithelial malignant neoplasm that arises from the liver. "To examine the molecular function of CCNDBP1 on liver cancer cells, we produced CCNDBP1-overexpressing cell lines by transfecting plasmid DNA-expressing human CCNDBP1 into cancer cell lines of HLE and HepG2." (PMID 35160302, 2022). "Previous studies reported that CCNDBP1 was correlated with the occurrence and development of breast cancer, colon cancer, liver cancer, non-small cell lung cancer, osteosarcoma, and gastric cancer." (PMID 34631521, 2021). "Therefore, this study aimed to investigate the molecular mechanisms of CCNDBP1, focusing on the recovery from DNA damage of liver cancer cells and in Ccndbp1 knockout mice." (PMID 35160302, 2022).
osteosarcoma (3 papers, 2016 to 2021). A usually aggressive malignant bone-forming mesenchymal neoplasm, predominantly affecting adolescents and young adults. "The influence of CCNDBP1 on the Rb/E2F signaling pathways and G2M checkpoint regulation has been reported in osteosarcoma." (PMID 34631521, 2021).
breast carcinoma (2 papers, 2016 to 2021). "In breast cancer, the decrease in CCNDBP1 expression was correlated with the poor prognosis of patients." (PMID 34631521, 2021). "Moreover, in some progressive or metastatic cancer tissues (including breast cancer, prostatic cancer, and colon cancer), CCNDBP1 expression declined." (PMID 34631521, 2021).
metastatic tumor (2 papers, 2014 to 2021). "CCNDBP1 is an independent prognostic factor for the PFS in our cohort, mainly related to metastatic tumor patients at baseline characteristics." (PMID 34631521, 2021).
atherosclerosis (1 paper, 2025). A disease characterized by the build-up of fatty material and calcium deposition in the arterial wall resulting in partial or complete occlusion of the arterial lumen. "Applying MAGEIT to a genome-wide analysis of gene–alcohol interactions on hypertension and seated systolic blood pressure in the Multiethnic Study of Atherosclerosis revealed genes like EIF2AK2, CCNDBP1, and EPB42 influencing blood pressure through alcohol interaction." (PMID 39538414, 2025).
colitis (1 paper, 2022). Inflammation of the colon. "In conclusion, Ccndbp1 contributed to Atm–Chk2 pathway activation in the DSS-induced colitis mouse model, causing inflammation and apoptosis of mucosal cells in the colon." (PMID 35806959, 2022). "We assessed the effect of DSS-induced colitis on colon length, disease activity index, and histological score and on the Atm–Chk2 pathway and the subsequent apoptosis in Ccndbp1-knockout mice." (PMID 35806959, 2022). "In conclusion, Ccndbp1 contributed to the activation of the Atm–Chk2 pathway in the DSS-induced colitis mouse model, triggering inflammation and apoptosis of mucosal cells in the colon." (PMID 35806959, 2022). "Based on the results that Ccndbp1 depletion helped ameliorate DSS-induced colitis, the involvement of Atm–Chk2 pathway signaling in this disease was examined using the Ccndbp1-knockout mice." (PMID 35806959, 2022). "To determine the role of Ccndbp1 and the Atm–Chk2 pathway in DSS-induced colitis, we examined the effect of DSS-induced colitis on Ccndbp1-knockout mice." (PMID 35806959, 2022). "In addition, considering that the DSS-induced colitis mouse model is the animal model for human colitis including UC, further analyses of the role of Ccndbp1 in humans will also reveal the potential novel therapy that targets this molecule." (PMID 35806959, 2022). "Therefore, Ccndbp1 contributed to activating the Atm–Chk2 pathway in DSS-induced colitis, as seen in the hepatocytes." (PMID 35806959, 2022). "Therefore, our study is the first to report that Ccndbp1 is involved in the pathogenesis of DSS-induced colitis in the acute phase via the Atm–Chk2 pathway and related apoptosis." (PMID 35806959, 2022). "Our results demonstrated that Ccndbp1 depletion ameliorated DSS-induced colitis in mice." (PMID 35806959, 2022). "Thus, DSS-induced colitis in the epithelium was milder in Ccndbp1-knockout mice." (PMID 35806959, 2022). "Thus, this study aimed to examine the contribution of Ccndbp1 and the Atm–Chk2 pathway in DSS-induced colitis." (PMID 35806959, 2022). "Our study results further showed that the colon length, histological inflammation, and DAI after DSS treatment were milder in Ccndbp1-knockout mice than in wild-type mice, consistent with the evidence that the pathology of DSS-induced colitis involves the double-strand DNA damage." (PMID 35806959, 2022). "Therefore, we aimed to examine the contribution of Ccndbp1 and the Atm–Chk2 pathway in DSS-induced colitis." (PMID 35806959, 2022).
colorectal cancer (1 paper, 2022). A primary or metastatic malignant neoplasm that affects the colon or rectum. "Furthermore, CCNDBP1 methylation in cancer cells was reported to be related with the chemosensitivity of colorectal cancer to 5-fluorouracil, suggesting that CCNDBP1 expression in cancer cells might be related with tumor viability upon the initiation of antitumor agents." (PMID 35160302, 2022).
Hypertension (1 paper, 2025). The presence of chronic increased pressure in the systemic arterial system. "While no genes reached genome-wide significance in the hypertension analysis, MAGEIT_RAN yielded the 2 lowest P-values among the 5 methods tested and identified 2 genes, CCNDBP1 and EPB42, located at the cytogenetic region 15q15.2, previously reported to be associated with blood pressure." (PMID 39538414, 2025).
liposarcoma (1 paper, 2021). A usually painless malignant tumor that arises from adipose tissue. "The present study aimed to explore the prognostic value, function, and mechanism of CCNDBP1 in dedifferentiated liposarcoma (DDL)." (PMID 34631521, 2021).
sarcoma (1 paper, 2021). A usually aggressive malignant neoplasm of the soft tissue or bone. "CCNDBP1 had an improved prognostic value in 58 patients with DDL in the TCGA database and all the sarcoma patients in the GEIPA database." (PMID 34631521, 2021). "Among these genes, only CCNDBP1 and VPS18 affect both the OS and DFS in patients with sarcoma, and the FC of CCNDBP1 is higher than that of VSP18 in our sequencing data." (PMID 34631521, 2021).
tumor (11 papers, 2014 to 2025). "This function is strengthened by the fact that CCNDBP1 expression is significantly higher in normal lung tissues than tumor ones." (PMID 37058478, 2023). "CCNDBP1 functions as a tumor suppressor as it negatively regulates TGF-β signal-induced cell migration depending on the surrounding condition." (PMID 35160302, 2022). "Next, we analyzed the correlation between the CCNDBP1 protein expression level and clinical staging of patients, and determined that the more advanced the clinical stage, the lower the CCNDBP1 expression level in the tumor tissues of the patients." (PMID 34631521, 2021). "This is the first study reporting that CCNDBP1 is a tumor suppressor gene of DDL and putative prognostic marker in DDL patients." (PMID 34631521, 2021). "Univariate analysis indicated that with the AOD value of 0.1950 as the boundary, the low CCNDBP1 protein expression level (P = 0.0016), clinical-stage IV (P < 0.0001), and tumor site (P = 0.0194) were correlated with the short PFS of the patients." (PMID 34631521, 2021). "Besides lung, CCNDBP1 has been proposed to be a tumor suppressor gene for multiple tissues, including prostate, breast, liver, ovary, lymph, retina, colon, neuroglial, bone and lens epithelial cell through interacting with different proteins." (PMID 37058478, 2023). "In summary, CCNDBP1 is a major tumor suppressor of DDL and could be used as a prognostic marker for the prediction of DDL metastasis." (PMID 34631521, 2021). "As EMT (Epithelial-Mesenchymal Transition) was deemed as the key step for tumor cells to obtain the invasion and metastasis capacities, we speculate that CCNDBP1 may be related to the EMT process." (PMID 34631521, 2021). "In addition to the tumor suppressive character of ATM/Chk2 signaling, recently, CCNDBP1 (cyclin D1 binding protein 1), a protein associated to chemotherapy-induced damage rescuing, has been found as a possible linker between the ATM/Chk2 signaling and chemoresistance." (PMID 40422251, 2025). "Therefore, management of CCNDBP1 expression in the tumor may recover the sensitivity to anticancer therapy." (PMID 35160302, 2022). "Cyclin D1 binding protein 1 (CCNDBP1) is considered a tumor suppressor, and when expressed in tumor cells, CCNDBP1 can contribute to the viability of cancer cells by rescuing these cells from chemotherapy-induced DNA damage." (PMID 35160302, 2022). "In order to further verify the role of CCNDBP1 as a tumor suppressor in DDL, we conducted in vitro experiments and found that CCNDBP1 significantly inhibited the clone formation, proliferation, migration, and invasion capacities of DDL cell lines." (PMID 34631521, 2021). "Cluster 1 was characterized by upregulation of tumor-suppressing genes: HNF1B, CCNDBP1, PATJ, EPB41L3, MARVELD2, PTEN in conjunction with cell-cycle genes – GSPT1, GPR19, EAPP, KIT, CDKL1, and stem cell markers – RBBP5, NANOG, NCSTN, ERG, including quiescent stem cell markers—FOXP1, SMARCA2." (PMID 36348001, 2022). "In lung cell, CCNDBP1 has been proposed to repress ID1 (inhibitor of DNA binding 1, HLH protein) expression, inactivate of PI3K/Akt signaling pathway and further suppress cell proliferation, migration, invasion and tumorigenesis, thus effecting as a tumor suppressor." (PMID 37058478, 2023). "Therefore, the expression of CCNDBP1 might not be tumor-specific." (PMID 34631521, 2021).
cancer (6 papers, 2015 to 2023). A tumor composed of atypical neoplastic, often pleomorphic cells that invade other tissues. "The direct interaction of MEK2 was recently reported to phosphorylate CCNDBP1 at its Ser313 and Ser356 residues, thereby promoting its turnover by ubiquitin-mediated proteasomal degradation, which led to cancer cell proliferation, migration, and invasion." (PMID 35160302, 2022). "CCNDBP1 significantly inhibited the clone formation, proliferation, migration, and invasion of cancer cells in vitro and promoted cancer cell apoptosis." (PMID 34631521, 2021). "Considering the role of rs66651343 and rs12909095 on CCNDBP1 expression regulation, these two SNPs may contribute to the different response of these two agent types among cancer patients, which deserves further investigation." (PMID 37058478, 2023). "Therefore, this study focused on investigating the function of CCNDBP1, which is directly related to the survival of cancer cells by escaping DNA damage and chemoresistance." (PMID 35160302, 2022). "A total of three differentially hypermethylated genes (CCNE1, PON3, and CCNDBP1) and two differentially hypomethylated genes (DDX43 and CHL1) were selected for the validation based on their β-value and association with CRC as well as other cancers." (PMID 28243201, 2017). "Cyclin D type binding protein 1 (CCNDBP1), also known as GC1P, is a tumor suppressor gene that is downregulated in some cancers such as breast and prostate." (PMID 28243201, 2017). "Indeed, our results demonstrated that CCNDBP1 overexpression in HCC contributed to higher cell growth and resistance to X-ray-induced DNA damage and that this mechanism was dependent on the activation of the ATM–CHK2 pathway in cancer cells." (PMID 35160302, 2022). "However, the function of CCNDBP1 that is directly related with the survival from DNA damage and chemoresistance in cancer cells has not been investigated." (PMID 35160302, 2022). "On the one hand, limited by conditions, we could not conduct in vivo experiments to further confirm the anti-cancer effect of CCNDBP1 in DDL, thereby necessitating follow-up studies." (PMID 34631521, 2021).
CCNDBP1 also shares sentences with these, for which no sentence is quoted: gastric cancer (2 papers); lung carcinoma (2); non-small cell lung carcinoma (2); adenocarcinoma (1); Brain atrophy (1); chlamydial infection (1); colon cancer (1); hepatocellular adenoma (1); metastatic cancer (1); prostatic cancer (1); retinal degeneration (1); squamous cell carcinoma (1); Stroke (1); ulcerative colitis (1); Wilson disease (1).